RP9 (RP9 pre-mRNA splicing factor)
Description:
Is thought to be a target protein for the PIM1 kinase. May play some roles in B-cell proliferation in association with PIM1 (By similarity).
Synonyms: PAP-1; PAP1
Tractability: PROTAC: UniProt records ubiquitination sites on it; ubiquitination databases record sites on it.
Gene: Protein-coding gene on chromosome 7 (33,094,797 to 33,109,405, reverse strand). Ensembl gene ENSG00000164610.
Subcellular location: Nucleus
Subcellular location (Human Protein Atlas): Nucleoplasm; Cytosol; Vesicles
Gene Ontology:
Molecular function: protein binding; RNA binding
Biological process: cognition; RNA splicing
Cellular component: cytosol; nucleoplasm; nucleus; signal recognition particle receptor complex
Genetic constraint (gnomAD): Loss-of-function variants: 17 observed, 21.38 expected, observed/expected ratio (o/e) 0.8, 90% interval 0.54 to 1.19. The upper end of that interval is the gene's LOEUF score, 1.19, which puts it in group 5 of 6, group 1 being the genes least tolerant of losing a copy. Missense variants: 228 observed, 231.81 expected, observed/expected ratio (o/e) 0.98, 90% interval 0.88 to 1.1. Synonymous variants: 87 observed, 78.23 expected, observed/expected ratio (o/e) 1.11, 90% interval 0.93 to 1.33.
Gene-disease validity (ClinGen):
ClinGen rates the evidence that RP9 causes each of these diseases.
retinitis pigmentosa 9 (autosomal dominant): Limited.
Homologues: Orthologues: chimpanzee RP9 (99% identical), macaque RP9 (97% identical), pig RP9 (94% identical), dog RP9 (93% identical), mouse Rp9 (89% identical), rat Rp9 (88% identical), guinea pig RP9 (84% identical), rabbit RP9 (60% identical).
Diseases named in the same sentence as RP9 in open-access papers:
RP9 is named in the same sentence as 9 diseases in open-access papers, as found by Europe PMC text mining. Sharing a sentence is not in itself a finding about the gene and the disease. The quoted sentences say what the papers report.
retinitis pigmentosa (6 papers, 2011 to 2022). Retinitis pigmentosa (RP) is an inherited retinal dystrophy leading to progressive loss of the photoreceptors and retinal pigment epithelium and resulting in blindness usually after several decades. "Long-read SMRT sequencing of the deletion breakpoints also determined that the aberration included the neighboring RP9 gene implicated in retinitis pigmentosa; however, the clinical significance of this was considered uncertain given the paucity of reported cases with unambiguous RP9 mutations." (PMID 29367880, 2018). "Herein, we successfully generated Rp9 gene knockout (Rp9-KO) and point mutation knock in (Rp9-KI) (Rp9, c.A386T, P.H129L) which was analogous to the reported one in the retinitis pigmentosa patients (Rp9, c.A410T, P.H137L) in 661 W retinal photoreceptor cells by using CRISPR/Cas9-mediated approach." (PMID 28216641, 2017). "Here, we utilize the CRISPR/Cas9 system to generate both the Rp9 gene knockout (KO) and point mutation knock in (KI) (Rp9, c.A386T, P.H129L) which is analogous to the reported one in the retinitis pigmentosa patients (RP9, c.A410T, P.H137L) in 661 W retinal photoreceptor cells in vitro." (PMID 28216641, 2017). "Our findings reveal a functional relationship between the ubiquitously expressing RP9 and the disease-specific gene, thereafter provide a new insight of disease mechanism in RP9-related retinitis pigmentosa." (PMID 28216641, 2017). "Our study for the first time revealed a functional relationship between Rp9, the general splicing factor, and FSCN2, the photoreceptor-specific gene, and provided a new insight of disease mechanism in Rp9-causing retinitis pigmentosa." (PMID 28216641, 2017). "Mutations in genes encoding the splicing factors PRPF3, PRPF8, PRPF31, RP9, and SNRNP200 can cause non-syndromic retinitis pigmentosa, a severe form of inherited blindness leading to rod photoreceptor degeneration." (PMID 26985665, 2016). "By using patient-derived iPS cells and in vitro differentiation technology, we have shown that RP9-retinitis pigmentosa is involved, at least in part, in oxidative stress pathways; this has not been reported previously in any animals or cell models." (PMID 21347327, 2011).
autosomal dominant retinitis pigmentosa (3 papers, 2013 to 2023). Autosomal dominant retinitis pigmentosa (RP) is an autosomally dominant inherited retinal dystrophy leading to progressive loss of the photoreceptors and retinal pigment epithelium and resulting in blindness usually after several decades. "Mutations in the RP9 gene result in autosomal dominant retinitis pigmentosa (Maitaet al., 2004;Keenet al., 2002)." (PMID 37082000, 2023). "Mutations in the pre-mRNA splicing factor, RP9 (also known as PAP1), predispose autosomal dominant retinitis pigmentosa (adRP) with an early onset and severe vision loss." (PMID 28216641, 2017).
colorectal cancer (1 paper, 2022). A primary or metastatic malignant neoplasm that affects the colon or rectum. "The long non-coding RNA (lncRNA) RP9 pseudogene (RP9P) is a pseudogene-derived lncRNA that has never been reported in cancer, and its function underlying tumorigenesis in colorectal cancer (CRC) remains unknown." (PMID 35600345, 2022).
retinal disease (1 paper, 2021). "A subset of patients was screened for mutations in retinal disease genes, and mutations in the following genes were found: three cases with USH2A; three cases with EYS; one case each with USH3A (CLRN1), DHX38, RHO, RPGR, and RP9." (PMID 33037922, 2021).
RP9 also shares sentences with these, for which no sentence is quoted: cancer (1 paper); congenital stationary night blindness (1); hereditary retinal dystrophy (1); progressive external ophthalmoplegia (1); syndromic (1).